TNFAIP3 (TNF alpha induced protein 3)
Diseases named in the same sentence as TNFAIP3 in open-access papers (continued):
Sharing a sentence is not in itself a finding about the gene and the disease.
MALT lymphoma (17 papers, 2012 to 2023). An indolent, extranodal type of non-Hodgkin lymphoma composed of small B-lymphocytes (centrocyte-like cells). "While the number of patients is small and especially the subgroup of patients with MALT lymphomas is limited, these data are in line with the results reported for ibrutinib in terms of potential impact of TNFAIP3 and KMT2D mutations." (PMID 37389189, 2023). "For example, ocular adnexal MALT lymphoma features frequent mutations of TNFAIP3 and MYD88, while those from the thyroid commonly showed TNFRSF14 and TET2 mutations." (PMID 34203889, 2021). "In fact, somatic mutations of TNFAIP3 (A20) protein, which plays a key role in controlling NF-κB activation, have been observed in the MALT lymphoma subtype frequently associated with SS." (PMID 25759795, 2015). "Lymphoid malignancies such as diffuse large B-cell lymphoma, marginal zone lymphoma, follicular lymphoma, MALT lymphoma and Hodgkin lymphoma, often carry deletions or inactivating point mutations in TNFAIP3 suggesting a role for TNFAIP3 as a tumor suppressor." (PMID 24039598, 2013). "Moreover, TNFAIP3 inactivation by deletion or mutation was significantly higher in MALT lymphomas with IGHV4-34 rearrangement (54%), particularly in those of OAMZL (70%), than in those using other IGHV genes (20%)." (PMID 35008340, 2021). "In MALT lymphomas, mutations of TNFAIP3 and CREBBP (22% vs. 8%) are more frequent than in SMZLs." (PMID 34590593, 2021). "The TNF-α-induced protein 3 gene (TNFAIP3, A20), which was identified as the target of 6q23 deletion in MALT lymphoma, is an important inhibitor of NF-κB." (PMID 36614921, 2022). "For instance, deletion of TNFAIP3 (A20) was detected in MALT lymphomas of the ocular adnexa (19%), thyroid (11%), salivary gland (8%), and liver (0.5%), but not in the lung, stomach, and skin." (PMID 35008340, 2021). "Among MALT lymphoma of various sites, the most prominent findings were frequent CD274 (52.6%), TNFRSF14 (52.6%), TET2 (85.5%) and TNFAIP3 (30%) mutations in the thyroid cases." (PMID 34021249, 2021). "Apart from the typical chromosomal translocations, TNFAIP3 (A20) has been identified as frequently deleted in ocular adnexal MALT lymphoma as detected by array comparative genomic hybridization." (PMID 25922601, 2015). "In H. pylori-positive gastric MALT lymphomas unresponsive to eradication therapy, NF-κB pathway mutations, including TNF-receptor-associated factor 3 (TRAF3) mutations and TNF-alpha-induced protein 3 (TNFAIP3) mutations, and MALT1 translocations are enriched." (PMID 35053607, 2022). "In the present study, we again confirm that NF-κB activation is a major driver in the pathogenesis of H. pylori negative MALT lymphoma, as shown by highly frequent translocations and TNFAIP3 inactivating mutations." (PMID 34203889, 2021). "Targeted sequencing confirmed that NF-κB activation is a major driver in the pathogenesis of H. pylori negative MALT lymphoma, as shown by frequent TNFAIP3 inactivating mutations and also by translocations of MALT1/IGH." (PMID 34203889, 2021). "Whereas 3q and 18q gains were common in all three subtypes, del(6q23)(TNFAIP3) could be used for differentiation between MALT lymphoma and splenic MZL." (PMID 25922601, 2015). "TNFAIP3 is the most frequently mutated gene in H. pylori negative gastric MALT lymphoma.TNFAIP3, a negative regulator of NF-κB, was the most frequently affected gene, with mutations detected in 23% (8/35) of cases, including one case carrying two mutations (both frameshift deletions)." (PMID 34203889, 2021). "Four genes recently described to be mutated in the non-pSS MALT lymphoma of the salivary gland, TBL1XR1, CCR6, TNFAIP3 and NOTCH2, were also mutated in a subset of our pSS-MALT lymphomas." (PMID 35205758, 2022).
MALT lymphoma (continued). "Beyond TNFAIP3 and MYD88 mutations, MALT lymphoma shows rare or no mutations in other members of NF-kB pathway such as CD79A, CD79B, CARD11, BIRC3, and TNFRSF11A, which are frequently seen in other B-cell lymphomas with constitutive NF-kB activation." (PMID 35008340, 2021). "Furthermore, frequent TNFAIP3 inactivating mutations and translocations in MALT1/IGH have been detected in H. pylori-negative gastric MALT lymphoma, suggesting that the NF-κB pathway can be a major driver in the pathogenesis of this group." (PMID 35053607, 2022). "In a small series of four pSS patients with cryoglobulinemia but without MALT lymphoma, pathogenic mutations in small fractions of circulating B-cells were observed in genes that are often associated with common B-cell lymphomas, such as CARD11, TNFAIP3, CCND3, ID3, BTG2 and KLHL6." (PMID 35205758, 2022).
Arthritis (16 papers, 2011 to 2025). Inflammation of a joint. "We use the in vivo mouse model A20myel-KO, characterized by the deletion of the potent anti-inflammatory factor A20 (TNFAIP3) specifically in the myeloid cells, the excessive type-1 cytokine production, and the development of spontaneous arthritis." (PMID 38680500, 2024). "Tnfaip3, Ptpn6 and Irak3 were differentially expressed in affected paws, spleens, lymph nodes and circulating leucocytes in experimental murine arthritis treated with anti-TNF." (PMID 39116634, 2024). "Altered expression of the NF-κB suppressor gene A20/TNFAIP3 has been found in monocytes from RA patients, and myeloid-cell-specific deletion of A20 in mice triggers spontaneous arthritis." (PMID 35628185, 2022). "Collectively, the results show that deletion of the TT>A enhancer at the TNFAIP3 locus results in an autoimmune/inflammatory phenotype most clearly evident as arthritis." (PMID 29440643, 2018). "In arthritis subjects, decreased basal levels of TNFAIP3 results in greater fold induction of NF-κB upon stimulation." (PMID 28791018, 2017). "have shown that arthritis pathology is critically related to the NLRP3 inflammasome/IL-1 signaling axis, in the arthritis model A20myel-KO mice, in which the A20/Tnfaip3 RA susceptibility gene is deleted in myeloid cells." (PMID 26385789, 2015). "Through stratified analysis, TNFAIP3 and ETS1 showed significant associations with multiple SLE subphenotypes (such as malar rash, arthritis, hematologic disorder and antinuclear antibody) while TNIP1 just showed relatively weak association with onset age." (PMID 22087647, 2011). "“C” is a 12-year-old girl with a heterozygous mutation TNFAIP3 c.811C>T (p.Arg271*) (HLA B51 negative) whose predominant symptoms include oral and genital ulcers, arthritis, and uveitis." (PMID 40822695, 2025). "TNFAIP3 encodes the (de)ubiquitinating enzyme A20 that inhibits tumor necrosis factor (TNF)-induced activation of nuclear factor kappa-B (NF-κB), and TNFAIP3 gene-deficient mice develop spontaneous arthritis." (PMID 37511889, 2023). "Downregulation of TGF-β1, Furin, and TNFAIP3 by miR-24 and miR-125a-5p may deteriorate the arthritis." (PMID 23874885, 2013). "Recently, high penetrance heterozygous germline mutations in TNFAIP3 were considered as the cause of an auto-immune related syndrome Haplo insufficiency of A20 (HA20), displaying early-onset systemic inflammation, arthralgia/arthritis, oral/genital ulcers and ocular inflammation." (PMID 28031783, 2016).
multiple sclerosis (16 papers, 2014 to 2024). A progressive autoimmune disorder affecting the central nervous system resulting in demyelination. "Mutations in A20/TNFAIP3 are associated with a variety of autoimmune diseases, including multiple sclerosis (MS)." (PMID 37856217, 2023). "Single nucleotide polymorphisms in TNFAIP3 locus have been associated to autoimmune inflammatory disorders, including Multiple Sclerosis (MS)." (PMID 32325694, 2020). "Some of the differentially regulated genes, such as the IL-7 receptor (Ilr7), tumor necrosis factor receptor superfamily 12, TNFRSF12/DR3 and TNF alpha induced protein 3 (TNFAIP3) are known to confer susceptibility to multiple sclerosis." (PMID 25269445, 2014). "Likewise, fumarates had differing effects on the expression of key genes that have been linked to multiple sclerosis (e.g., TNFAIP3, CXCL8, IL6, and IRF1)." (PMID 35455458, 2022). "TNFAIP3 was also suggested to play a role in multiple sclerosis (MS), as TNFAIP3 was downregulated in the blood of MS patients." (PMID 39125844, 2024). "For instance, multiple sclerosis (MS), an autoimmune disorder leading to muscle spasms, stiffness and weakness, has been linked to changes in USP18, TNFAIP3 (A20) and USP16 expression levels." (PMID 38716888, 2024). "Previous studies have reported that TNFAIP3 overexpression can promote oxygen-free radical generation and ferroptosis and may relate to neurodegenerative diseases, such as multiple sclerosis and Parkinson’s disease." (PMID 36118694, 2022).
COVID-19 (13 papers, 2020 to 2025). A disease caused by infection with severe acute respiratory syndrome coronavirus 2. "A recent familial case report contextualised aphthous stomatitis within PFAPA syndrome (periodic fever, aphthous stomatitis, pharyngitis, and cervical adenitis), attributing it to a TNFAIP3 mutation with potential modulation by environmental factors, including COVID-19 vaccination." (PMID 40684682, 2025). "A few genes, as NFKBIA, ICAM1, CXCL8, and TNFAIP3 are involved in NF-κB signaling and TNF signaling pathways, which have been known to cause inflammation and cytokine storms, augmenting COVID-19 severity." (PMID 37701571, 2023). "A third module (c) revolves around TNF and includes IL1A, IL1B, TNFSF14, TNFAIP3, and CSF2 that likely mediates the inflammatory response associated with COVID-19 progression." (PMID 35085325, 2022). "Concordantly, for downstream genes of AP-1, the expression levels of some chemokine genes (e.g., CCL2, CXCL1, CXCL2, and CXCL10) were downregulated, while the expression levels of immune negative regulation genes (e.g. BCL3, NFKBIA, SOCS3, and TNFAIP3) were upregulated during the COVID-19 recovery." (PMID 33361761, 2020). "Our study found that COVID-19 patients have upregulated pathways in apoptotic signaling pathways and response to virus/viral process, including genes TNF, TNFAIP3, TNFSF10, TNFRSF1B, TNFRSF1." (PMID 37949875, 2023). "Genes that were found to be upregulated in the early COVID-19 mortality cases and involved with the interferon (ISG20, IRF1, GBP2) and NF-κB (NFKB2, NFKBIA, TNFAIP3) pathways showed linear decline with longer symptomatic interval." (PMID 35446789, 2022).
systemic sclerosis (13 papers, 2014 to 2025). A chronic disorder, possibly autoimmune, marked by excessive production of collagen which results in hardening and thickening of body tissues. "Three intronic variants and one exonic variant of the TNFAIP3 gene have been linked to systemic sclerosis (rs5029939, rs58905141, rs117480515, rs2230926)." (PMID 38790215, 2024). "Indeed, several genetic variants within the TNFAIP3 locus have been implicated in systemic sclerosis (SSc)." (PMID 41181125, 2025). "TNFAIP3 and TNIP1, which are ubiquitin-related genes, have been shown to be correlated with SLE, RA, and systemic sclerosis (SSc)." (PMID 35265070, 2022).
colitis (11 papers, 2019 to 2025). Inflammation of the colon. "P35K EVs enhanced innate immunity, while P100K EVs downregulated colitis-associated miRNAs, particularly miR-125b, and increased expression of TNFAIP3 (A20)." (PMID 39885215, 2025). "Transgenic mice expressing tumor necrosis factor induced protein 3 (TNFAIP3; aka A20) in intestinal epithelial cells under the villin promoter (v-TNFAIP3) develop colitis on the recombination activating 1 (RAG1) deficient background (v-TNFAIP3 x RAG1-/-)." (PMID 38512959, 2024). "Mice expressing tumor necrosis factor-induced protein 3 (TNFAIP3) in intestinal epithelial cells (villin-TNFAIP3) develop colitis when interbred with Recombination Activating 1-deficient mice (RAG1−/−)." (PMID 36162004, 2022). "miR-19a promoted colitis and colitis-associated colon cancer by downregulating TNFAIP3 in a targeted manner and constitutively activating NF-κB signaling." (PMID 32308549, 2020). "Also, intestinal and myeloid deletion of A20 (TNFAIP3, encoded by Tnfaip3 in mice, Tnfaip3ΔIEC/Δmyel), an inhibitor of NF‐κB and apoptosis, induces ileitis and severe colitis characterized by IEC apoptosis, goblet cell, and PC loss." (PMID 36573340, 2023). "Also, P35K EVs modulated innate immunity, while P100K EVs decreased inflammation through the downregulation of colitis-associated microRNAs, especially miR-125b, associated with a higher expression of the NFκB inhibitor TNFAIP3 (A20)." (PMID 31601878, 2019). "Specifically, differential expressed genes (DEGs) related to colitis such as Mmp10, Tnfaip3, Lcn2, Serpine1, and Pla2g4f were upregulated in the colon tissue of colitis mice in DVF group." (PMID 38172943, 2024). "The colitis in villin-TNFAIP3 × RAG1−/− (TRAG) mice is prevented by antibiotics, indicating a role for microbes in this innate colitis." (PMID 36162004, 2022). "Remarkably, a study by Ma and Malynn showed that induction of TNFAIP3 expression has provided protection against experimental colitis in mice." (PMID 31120955, 2019). "In order to better understand innate immune contributions to IBD, we developed a model of spontaneous 100% penetrant, early onset colitis that occurs in the absence of adaptive immunity by crossing villin-TNFAIP3 mice to RAG1-/- mice (TRAG mice)." (PMID 38512959, 2024). "Despite this microbial invasion, v-TNFAIP3 mice do not develop colitis." (PMID 38512959, 2024). "The specific deletion of Tnfaip3 only in epithelial cells (Tnfaip3ΔIEC) does not have a pathological phenotype but sensitize these mice to DSS‐induced colitis and TNF‐induced apoptosis: 24 h after injection of a sublethal TNF dose, LYZ‐containing PCs and expression of PC‐specific AMPs were reduced." (PMID 36573340, 2023). "Microbial invasion was observed in villin-TNFAIP3 mice, which do not develop colitis." (PMID 36162004, 2022).
diabetes (11 papers, 2014 to 2025). "TNFAIP3 mutations, such as Arg87Ter, Val489Aal fs7, Gln490Ter, are His577Alafs95, were related to BD-like symptoms and type 1 (T1D) diabetes, suggesting that A20 haploinsufficiency may be related to the onset of diabetes." (PMID 39125844, 2024). "Subsequent pathway analysis demonstrated that TNFAIP3 upregulation influenced diabetes-related pathways and immune responses." (PMID 40646297, 2025). "HUANG_FOXA2_TARGETS_UP comprises 45 genes, some of which have been suggested to be implicated in the development of diabetes, such as KAT2B and TNFAIP3." (PMID 28744461, 2017). "Therefore, this project intends to further take up TNFAIP3 as an effective target employing lentivirus as a vector to explore the effect and mechanism of upregulating TNFAIP3 on diabetic neuropathic pain." (PMID 34853620, 2021). "However, reports of the effect of lentivirus-based TNFAIP3 expression augmentation on diabetic neuropathic pain are scarce." (PMID 34853620, 2021).
lung carcinoma (11 papers, 2015 to 2025). "In A549 lung cancer cells, TNFAIP3 exhibited a significant induction of ferroptosis." (PMID 40469292, 2025). "Recent studies suggested that TNFAIP3 may have a vital role in the invasion and proliferation of lung cancer and gastric cancer." (PMID 36647133, 2023). "Knock out of TNFAIP3 enhances proliferation and invasion of lung cancer cells." (PMID 35984577, 2022). "Furthermore, silencing TNFAIP3 promoted lung cancer invasion and proliferation." (PMID 40469292, 2025). "In addition, miR-127 inhibits the proliferation and invasion of gastric cancer cells via Wnt7a, inhibits ovarian cancer cell proliferation by downregulating MAPK4, regulates the NF-κB pathway through TNFAIP3, and induces epithelial-mesenchymal transformation in lung cancer." (PMID 36371182, 2022). "Similarly, TNF alpha-induced protein 3 (TNFAIP3; also known as A20)-binding to ACSL4 promotes ferroptosis in lung cancer A549 cells." (PMID 37372148, 2023). "Our results revealed that miR-19a downregulates the target genes FOXP1, TP53INP1, TNFAIP3, and TUSC2 and that these genes might play important roles in the tumorigenesis of lung cancer; however, the invasion inhibition potency was found to differ among the four genes." (PMID 26367773, 2015).
Sjögren’s syndrome (11 papers, 2018 to 2025). "Epithelial Keratin 14-specific deletion of TNFAIP3 induces a Sjögren Syndrome-like in mice, recapitulating immune infiltration and a decrease in saliva production." (PMID 36091713, 2022). "TNFAIP3 (or A20) is a negative regulator of NFkB and polymorphisms in the TFNAIP3 gene, which has been associated with autoimmune diseases, including Sjögren Syndrome." (PMID 36091713, 2022).
asthma (10 papers, 2017 to 2025). "Clinical trials confirmed the immune regulatory association of TNF-α-induced protein 3 (TNFAIP3; A20) and asthma in humans." (PMID 38218816, 2024). "Genome-wide association studies of large patient cohorts indicated that the TNFAIP3 gene should be considered as an asthma susceptibility locus." (PMID 37056760, 2023). "Moreover, we recently showed that uncontrolled Tnfaip3‐deficient cDC1 activity suppressed Tc2 cell formation via IFNγ in a HDM‐driven asthma model." (PMID 40016948, 2025). "Moreover, the authors observed a positive association between a polymorphism in the TNFAIP3 gene and susceptibility to asthma in the cohort of GABRIELA [Multidisciplinary Study to Identify the Genetic and Environmental Causes of Asthma in the European Community (GABRIEL) Advanced Study]." (PMID 28261214, 2017). "In this section, we summarize the phenotypes of existing asthma mouse models that specifically entail depletion of the Tnfaip3 gene in different cell types as well as the critical TNFAIP3 SNPs in asthmatic patients." (PMID 37056760, 2023). "More recently an important upstream regulator of NF-kB signaling, TNFAIP3 (A20), was found to be vital in development of protection to asthma in rural children exposed to LPS." (PMID 33836776, 2021). "Deleting Tnfaip3 in the majority of macrophages, monocytes, neutrophils, and cDCs as well as moDCs resulted in Th1/Th17‐driven neutrophilic airway inflammation in a HDM model of asthma." (PMID 40016948, 2025). "Interestingly, we showed that HDM‐driven neutrophilic airway inflammation in mice carrying Tnfaip3‐deficient cDCs was independent of IL‐17, supporting the concept that neutrophilic airway inflammation in asthma models can be IL‐17‐independent and may involve Th1 cells or HMGB1‐producing ILC2s." (PMID 40016948, 2025).